GIMAP4 (GTPase, IMAP family member 4)
Description:
During thymocyte development, may play a role in the regulation of apoptosis (By similarity). GTPase which exhibits a higher affinity for GDP than for GTP.
Synonyms: IAN-1; IAN1; IMAP4; MSTP062; HIMAP4; FLJ11110
Tractability: Small molecule: a structure with a bound ligand is known. PROTAC: ubiquitination databases record sites on it; its protein half-life has been measured.
Gene: Protein-coding gene on chromosome 7 (150,567,242 to 150,573,962, forward strand). Ensembl gene ENSG00000133574.
Subcellular location: Cytoplasm, cytosol
Subcellular location (Human Protein Atlas): Cytosol; Vesicles
Gene Ontology:
Molecular function: GTPase activity; GTP binding
Cellular component: cytosol
Genetic constraint (gnomAD): Loss-of-function variants: 8 observed, 11.99 expected, observed/expected ratio (o/e) 0.67, 90% interval 0.39 to 1.2. The upper end of that interval is the gene's LOEUF score, 1.2, which puts it in group 5 of 6, group 1 being the genes least tolerant of losing a copy. Missense variants: 361 observed, 380.24 expected, observed/expected ratio (o/e) 0.95, 90% interval 0.87 to 1.04. Synonymous variants: 136 observed, 138.58 expected, observed/expected ratio (o/e) 0.98, 90% interval 0.85 to 1.13.
Homologues: Orthologues: chimpanzee GIMAP4 (99% identical), macaque GIMAP4 (88% identical), dog GIMAP4 (66% identical), guinea pig GIMAP4 (61% identical), mouse Gimap4 (60% identical), rat Gimap4 (57% identical), pig GIMAP4 (55% identical). Paralogues in human: GIMAP7 (33% identical), GIMAP1 (32% identical), GIMAP2 (30% identical), GIMAP5 (30% identical), GIMAP6 (29% identical), GIMAP8 (28% identical), GIMD1 (14% identical).
Diseases named in the same sentence as GIMAP4 in open-access papers:
GIMAP4 is named in the same sentence as 27 diseases in open-access papers, as found by Europe PMC text mining. Sharing a sentence is not in itself a finding about the gene and the disease. The quoted sentences say what the papers report.
lung carcinoma (5 papers, 2021 to 2025). "Our study first linked expression of GIMAP4 in lung cancer tissues with immune components of TME and provide insight into potential GIMAP4-based prognosis prediction." (PMID 36246963, 2022). "GIMAPs are recognized as an important regulator in the carcinogenesis and development of lung cancer, but the function of GIMAP4 in the tumor microenvironment (TME) of lung cancers is unclear." (PMID 36246963, 2022). "In this study, we identified gene mutations and differentially expressed genes (DEG) that verify differences in GIMAP4 expression between lung cancers and normal lung tissues." (PMID 36246963, 2022). "The survival analysis of the GIMAP family was performed, and the results showed that high levels of GIMAP1, GIMAP2, GIMAP4, GIMAP5, GIMAP, GIMAP7 and GIMAP8 mRNA expression levels were associated with better overall survival of patients with lung cancer." (PMID 34604035, 2021). "Increasing evidence had revealed that GIMAP4 seemed to serve as a protective factor in several kinds of cancer, including lung cancer." (PMID 33553190, 2021). "The “new” autoantibodies in our panel target TAAs like DCTPP1, GIMAP4, WWP2, MGMT, KCMF1, and GDA, which have demonstrated links to lung cancer pathogenesis." (PMID 39661479, 2025). "CD44, GIMAP4, CD69, and CCL4L2 were among the most relevant contributing markers defining the predictive ML signatures on lung cancer samples." (PMID 40989699, 2025). "GIMAP4, a GTP-binding superfamily member, collaborates with caspases in programmed cell death and accelerates T-cell apoptosis, with its expression potentially impacting survival in lung cancer." (PMID 39661479, 2025).
asthma (4 papers, 2019 to 2025). "One polymorphism (rs13222905) in GIMAP4 was only associated to both asthma and allergic sensitization." (PMID 34071190, 2021). "The up-regulated genes have been previously associated with asthma; hyper-reactivity and allergy (CCR2, HRH2, PTEN); lung development and apoptosis (CHRNA7, RTKN2); and immune function (GIMAP4, GIMAP7, KLRC3 and CD99)." (PMID 30971730, 2019). "GIMAP4 was associated with allergic sensitization, while GIMAP5 was linked to asthma." (PMID 41042382, 2025).
cervical cancer (4 papers, 2021 to 2022). A primary or metastatic malignant neoplasm involving the cervix. "The research of Xu found that GIMAP4 as an immune-related biomarker was associated with the remodeling in cervical cancer tumor microenvironment and served as a potential predictor for distant metastasis." (PMID 36246872, 2022). "GIMAP4 plays a key role in cellular apoptosis and T-cell development, which can be used as a prognostic marker of cervical cancer." (PMID 35782114, 2022). "In cervical cancer, the prognostic potential of GIMAP4 has been identified, and the immunoscore of TICs is strongly related to GIMAP4." (PMID 36246963, 2022). "Finally, we identified that the model constructed by GIMAP4, GIMAP1, FGF13-AS1, EFEMP2, and DYNC2I2 could be used as the prediction model for the prognosis of cervical cancer." (PMID 35782114, 2022).
lymphopenia (3 papers, 2009 to 2025). Reduction in the number of lymphocytes. "It is therefore unlikely thatthe Gimap4 two-base pair deletionmutation in the DR.lyp/lyp rat is functionally relevant todevelopment of T1D or lymphopenia, rather it is likely an additional naturalisoform." (PMID 19421422, 2009). "While we can exclude theinvolvement of the members of the Gimap family proximal to D4Rhw6 (Gimap8, Gimap9, Gimap4, Gimap6, and Gimap7)in the development of lymphopenia, we cannot exclude that they may play a rolein the development of T1D." (PMID 19421422, 2009). "Gimap4 and Gimap1 each had one amino acid substitution of unlikely significance for lymphopenia." (PMID 19421422, 2009). "Therefore, Gimap4 appears to represent a candidate genetic factor that may contribute to lymphopenia and diabetes." (PMID 41042382, 2025).
type 1 diabetes (3 papers, 2010 to 2025). "Gene–gene interactions were noted between GIMAP4 and IL2RA, a known human type 1 diabetes risk gene, as well as between GIMAP5 and INS, a major type 1 diabetes risk gene strongly associated with insulin autoantibodies as the first appearing islet autoantibody." (PMID 41042382, 2025). "The unexpected finding that Gimap5, along with Gimap4, may regulate diabetes development in the BB rat is likely to translate into human type 1 diabetes autoimmunity." (PMID 41042382, 2025).
breast carcinoma (2 papers, 2022). "Significant changes of GIMAP4 were showed in breast cancer, cervical squamous cell carcinoma, LUAD, LUSC, etc." (PMID 36246963, 2022). "The outcomes revealed that two hub genes (SERPING1 and GIMAP4) were negatively correlated with breast cancer bone metastasis." (PMID 36246872, 2022). "Moreover, in breast cancer, GIMAP4 might be a protective factor." (PMID 36246963, 2022).
diabetes (2 papers, 2009 to 2025). "We conclude that there are a limited number of genetic factors, including but not limited to Gimap4 and Gimap5, that are related to the increase in IgE levels, insulitis, infiltration of CD3+ and ED1+ cells, and beta cell loss prior to diabetes onset in congenic sBBM Gimap5-DP rats." (PMID 41042382, 2025). "Although the effect of thisvariation is unknown, we did discover this same deletion in thenonlymphopenic, diabetes resistant F344 rat.F344 DNA introgressed through this interval on the DR.lyp/lyp background protectsfrom onset of T1D suggesting that the deletionmutation in Gimap4 is notdeleterious." (PMID 19421422, 2009).
lung adenocarcinoma (2 papers, 2022 to 2024). A carcinoma that arises from the lung and is characterized by the presence of malignant glandular epithelial cells. "In this study, we investigated the expression and variation of GIMAP4 in lung adenocarcinoma (LUAD), to explore its association with infiltration of immune cells." (PMID 36246963, 2022). "Similarly, in another type of gene, the gene RASSF2 was shown to be an oncogene for Ewing sarcoma, and high GIMAP4 expression could facilitate the TME of immune cells to detect tumor cells and inhibit the development of lung adenocarcinoma cells." (PMID 38688945, 2024).
melanoma (2 papers, 2021 to 2025). A malignant, usually aggressive tumor composed of atypical, neoplastic melanocytes. "We only found the factors in a follow-up cohort of immunotherapy for melanoma and found that GIMAP4 can be used as an independent prognostic factor after immunotherapy." (PMID 33854546, 2021).
non-small cell lung carcinoma (2 papers, 2020 to 2022). A group of at least three distinct histological types of lung cancer, including non-small cell squamous cell carcinoma, adenocarcinoma, and large cell carcinoma. "GIMAP4 expression declined in non-small-cell lung cancer (NSCLC), correlated with a poor overall survival (OS) in LUAD, indicating that GIMAP4 was a promising prognostic biomarker in LUAD." (PMID 36246963, 2022).
Immunodeficiency (1 paper, 2021). Failure of the immune system to protect the body adequately from infection, due to the absence or insufficiency of some component process or substance. "A region on Chr4 included three GTPase genes (GIMAP7, GIMAP4, and GIMAP8), IMAP family members that have been related to the primary immunodeficiency pathway and were shown to play a major role in feed utilization and the metabolism of lipids, sugars, and proteins in Jersey cattle." (PMID 33633776, 2021).
ovarian carcinoma (1 paper, 2018). A malignant neoplasm originating from the surface ovarian epithelium. "Analysis of the frequently observed proteins by ANOVA confirmed increases in mean precursor intensity in ZFN91, TRPM5, SIRT1, CHD6, RIMS1, LOC101930455 (XP_005275896), CCDC37 and GIMAP4 between ovarian cancer versus normal female and other diseases or controls by the Tukey–Kramer HSD test." (PMID 30598658, 2018).
T-cell acute lymphoblastic leukemia (1 paper, 2025). Acute lymphoblastic leukemia of T-cell origin. "GIMAP4 has been implicated in T cell biology and was found to be aberrantly activated in T-cell acute lymphoblastic leukemia, supporting a functional role in lymphocyte regulation." (PMID 41042382, 2025).
vasculitis (1 paper, 2021). "Guanosine-5′-triphosphatase IMAP family member 4 (GIMAP4) is a locus that strongly affects susceptibility to vasculitis." (PMID 33680092, 2021).
tumor (8 papers, 2018 to 2024). "To explore mechanism of GIMAP4 underlying tumor-immune regulation, we calculated the correlations between GIMAP4 and 5 ICPs (CD274, CTLA4, TIGIT, LAG3, and PDCD1) and identified similar trends in their expression." (PMID 36246963, 2022). "Meanwhile, our results also showed that GIMAP4 mutated more in the high-immunity group, confirming that its mutation could generate tumor-specific neoantigens and an activated immune system in CC." (PMID 33553190, 2021). "In this paper, we checked differential expression state of GIMAP4 among different tumor types and further found that GIMAP4 matters in the pathogenesis, development, and prognosis of LUAD." (PMID 36246963, 2022). "We applied the CIBERSORT method to further confirm the relationship between GIMAP4 expression and the immune component, constructing 21 types of immune cell profiles in CC cases and analyzing the proportion of tumor-infiltrating immune subtypes." (PMID 33553190, 2021). "Additionally, previous studies have proven that GIMAP4 is capable of generating tumor-specific neoantigens and activating the immune system." (PMID 36246963, 2022). "Additionally, the further results indicated that the GIMAP4 expression in the normal cases was remarkably higher than the tumor samples by the Wilcoxon rank sum test." (PMID 33553190, 2021). "Thus, we concluded that GIMAP4 might reverse the Th1/Th2 drifting effect and increase the immunity of Th1, which might provide a new clue to enhance anti-tumor immunotherapy and improve treatment." (PMID 33553190, 2021). "CD74, GIMAP4, HCST, and HLA-DMA not only showed good clinical phenotype correlation but also correlated with M2 type macrophages, tumor purity, and immune score." (PMID 33854546, 2021). "Interestingly, our data show a significant decrease in mRNA levels of GIMAP4, GIMAP6, GIMAP7 and GIMAP8 in BC tissues, compared to DCIS tissues, and non-tumor breast tissues from either women with or without BC (supplementary 2)." (PMID 32523132, 2020).
cancer (3 papers, 2005 to 2022). A tumor composed of atypical neoplastic, often pleomorphic cells that invade other tissues. "Considering its immune system regulating function, GIMAP4 might be a potential cancer suppressor target." (PMID 36246963, 2022).
GIMAP4 also shares sentences with these, for which no sentence is quoted: Allergy (1 paper); Autoimmunity (1); bacterial infections (1); Behcet Syndrome (1); cervical squamous cell carcinoma (1); depression (1); Ewing sarcoma (1); infection (1); neuronal ceroid lipofuscinosis (1); psychiatric disorder (1); viral infections (1).